KLK2 (kallikrein related peptidase 2)
Description:
Glandular kallikreins cleave Met-Lys and Arg-Ser bonds in kininogen to release Lys-bradykinin.
Synonyms: hGK-1; KLK2A2; hK2
Tractability: Small molecule: a structure with a bound ligand is known; a high-quality ligand is known. Antibody: its Gene Ontology location is reachable by antibodies, with high confidence; UniProt predicts a signal peptide or a membrane-spanning region. PROTAC: a small molecule that binds it is known.
Target class: Serine protease; Enzyme; Serine protease PA clan; Serine protease S1A subfamily; Protease
Gene: Protein-coding gene on chromosome 19 (50,861,568 to 50,880,567, forward strand). Ensembl gene ENSG00000167751.
Pathways (Reactome):
Extracellular matrix organization: Activation of Matrix Metalloproteinases
Metabolism of proteins: Regulation of Insulin-like Growth Factor (IGF) transport and uptake by Insulin-like Growth Factor Binding Proteins (IGFBPs)
Signal Transduction: Activated PKN1 stimulates transcription of AR (androgen receptor) regulated genes KLK2 and KLK3
Gene Ontology:
Molecular function: serine-type endopeptidase activity
Biological process: regulation of systemic arterial blood pressure; zymogen activation; proteolysis
Cellular component: extracellular exosome; extracellular region; secretory granule
Genetic constraint (gnomAD): Loss-of-function variants: 17 observed, 22.72 expected, observed/expected ratio (o/e) 0.75, 90% interval 0.51 to 1.12. The upper end of that interval is the gene's LOEUF score, 1.12, which puts it in group 4 of 6, group 1 being the genes least tolerant of losing a copy. Missense variants: 327 observed, 333.58 expected, observed/expected ratio (o/e) 0.98, 90% interval 0.89 to 1.07. Synonymous variants: 136 observed, 128.3 expected, observed/expected ratio (o/e) 1.06, 90% interval 0.92 to 1.22.
Homologues: Orthologues: chimpanzee KLK2 (98% identical), macaque KLK2 (93% identical), pig KLK1 (65% identical), mouse Klk1b1 (60% identical), mouse Klk1b11 (59% identical), mouse Klk1b3 (59% identical), mouse Klk1b21 (59% identical), mouse Klk1b24 (59% identical), mouse Klk1b5 (59% identical), mouse Klk1 (58% identical), mouse Klk1b9 (58% identical), mouse Klk1b26 (58% identical), and 18 more. Paralogues in human: KLK3 (77% identical), KLK1 (66% identical), KLK11 (42% identical), KLK5 (41% identical), KLK8 (41% identical), KLK7 (41% identical), KLK14 (41% identical), KLK12 (39% identical), KLK4 (37% identical), TMPRSS4 (30% identical), PRSS58 (29% identical), PRSS54 (20% identical).
Diseases named in the same sentence as KLK2 in open-access papers:
KLK2 is named in the same sentence as 34 diseases in open-access papers, as found by Europe PMC text mining. Sharing a sentence is not in itself a finding about the gene and the disease. The quoted sentences say what the papers report.
prostate carcinoma (92 papers, 2005 to 2025). A carcinoma that arises from epithelial cells of the prostate gland. "In prostate cancer, KLK2 and KLK4 have become valuable diagnostic tools and drug targets, as in the 4K test and with a promising new monoclonal Fab." (PMID 41516101, 2025). "Despite the documented association between KLK2 and prostate cancer progression, as well as its highly prostate-specific expression, KLK2 had previously been thought of as a secreted protease and therefore considered unsuitable for drug targeting." (PMID 40627156, 2025). "A more recent study reported that strong KLK2 IHC staining was associated with short metastasis-free survival and prostate cancer-specific survival." (PMID 39272956, 2024). "Recent studies have shown that KLK2 is involved in the development and metastasis of prostate cancer and is associated with the prognosis of patients." (PMID 37593117, 2023). "It has been reported that during prostate cancer, upregulation of the KLK2 gene is associated with cell proliferation, migration, invasion, angiogenesis and apoptosis resistance of malignant cells." (PMID 37232542, 2023). "Recent studies have found a single nucleotide polymorphism (SNP) in the KLK2 gene with an increased risk of prostate cancer." (PMID 37593117, 2023). "Herein, we first demonstrated how miR-378 exerts anti-prostate cancer (PCa) actions by influencing multiple target genes, including KLK2, KLK4, KLK6, and KLK14, which are implicated in PCa development, cell proliferation, and cell survival." (PMID 35681793, 2022). "Lower KLK2 is also correlated with prostate cancer risk and higher percentage of free PSA, both of which are related to lower total PSA." (PMID 33150763, 2020). "Recently, KLK2 has been implicated in carcinogenesis and tumor metastasis of prostate cancer, whereas it is a useful serum marker of prostate cancer due to its association with prostatic proliferative disorders and tissue specificity." (PMID 26582203, 2016). "Serum hK2 levels were significantly higher among cases (mean hK2 = 0.246 ng/mL) than controls (mean hK2 = 0.228 ng/mL, p = 0.02), and the rs198977 KLK2 SNP was significantly associated with prostate cancer." (PMID 25279276, 2014). "The KLK2 SNP rs198977 was found to be positively associated with hK2 levels and shown to predict prostate cancer at the time of repeat prostate biopsy." (PMID 25279276, 2014). "We also showed that single nucleotide polymorphisms (SNPs) of the KLK2 gene, which encodes for the hK2 protein have been shown to be associated with prostate cancer." (PMID 25279276, 2014). "Among pre-screened men undergoing a repeat biopsy, we have found an association between the KLK2 SNP rs198977 as well as serum hK2 levels and prostate cancer." (PMID 25279276, 2014). "The KLK2 SNP rs198977 was positively associated with hK2 levels and predicts prostate cancer at the time of repeat prostate biopsy." (PMID 25279276, 2014). "Moreover, the increased expression of KLK2 in tumor tissues is associated with the increased proliferation rate and decreased apoptosis index of prostate cancer cells." (PMID 37593117, 2023). "Within the down-regulated gene set, we note a number of genes that have previously been associated with increased proliferation in prostate cancer; these include kallikrein 2 (KLK2), long non-coding RNA prostate cancer associated transcript 1 (PCAT1), Vav guanine nucleotide exchange factor 3 (VAV3)." (PMID 33596994, 2021). "KLK2 over-expression has been associated with the promotion of prostate cancer cell growth." (PMID 32038103, 2020). "Previous targeting of prostate-specific antigen and human kallikrein-related peptidase 2, two related enzymes abundantly expressed in prostatic malignancies, with radioimmunoconjugates intended for diagnostic purposes, have proven successful in rodent prostate cancer (PCa) models." (PMID 26983637, 2016).
prostate carcinoma (continued). "To further validate KLK2 as a novel target for prostate cancer, we developed two T cell–based therapeutic agents: KLK2 × CD3, a bispecific antibody redirecting CD3+ T cells to KLK2-expressing prostate cancer cells, and KLK2-targeted CAR T cells." (PMID 40627156, 2025). "To reassess potential cell surface expression, we used an anti-KLK2 monoclonal antibody to test a prostate cancer cell line (VCaP) as well as dissociated bone metastases from patients with mCRPC." (PMID 40627156, 2025). "Our results using a large number of prostate cancer specimens are consistent with the notion of KLK2 as a therapeutic target in prostate cancer, with high levels of KLK2 expression maintained across the prostate disease spectrum from LPC to mCRPC." (PMID 40627156, 2025). "Next, we evaluated the in vivo antitumor activity of KLK2 × CD3 in a mouse xenograft model of prostate cancer." (PMID 40627156, 2025). "Our results confirm that KLK2 is highly expressed across the prostate cancer disease continuum and characterize KLK2 as a promising cell surface therapeutic target in prostate cancer." (PMID 40627156, 2025). "In vitro studies showed that KLK2 × CD3 and KLK2-targeted CAR T cells interacted with KLK2+ prostate cancer cells and induced T-cell activation and cytotoxicity." (PMID 40627156, 2025). "Despite the promising results of small molecule inhibitors targeting KLK2 in prostate cancer treatment, there are still many challenges in the development and application of these inhibitors." (PMID 40207180, 2025). "KLK2 is overexpressed in prostate cancer and plays a pivotal role in cancer progression, establishing it as a potential therapeutic target." (PMID 40207180, 2025). "In this study, we assessed the expression profile and cellular localization of KLK2 across disease stages of prostate cancer and characterized the therapeutic effect of three KLK2-targeting treatments in preclinical models of prostate cancer." (PMID 40627156, 2025). "Although KLK2 is traditionally described as a secreted protease, our results demonstrated its cell surface expression in both prostate cancer cell lines and patient-derived tumors." (PMID 40627156, 2025). "In this study, we systematically characterized KLK2 expression in prostate cancer, confirmed its cell surface expression, and demonstrated the preclinical efficacy of three KLK2-targeting therapeutics with distinct MoA." (PMID 40627156, 2025). "The preclinical efficacy of three KLK2-targeting therapeutics was characterized using in vitro prostate cancer cell lines, patient-derived material, and in vivo xenograft mouse models." (PMID 40627156, 2025). "To further characterize the KLK2 expression in prostate cancer, we analyzed protein level expression of KLK2 in LPC, mHSPC, and mCRPC tissue samples by IHC and mIF." (PMID 40627156, 2025). "In contrast, we observed minimal differences in the levels of prostate and prostate cancer-associated proteins, including KLKB1, KLK2, KLK3, ACP3, and SLC45A3, which are markers of conventional adenocarcinoma of the prostate." (PMID 39910169, 2025). "The preclinical data with 225Ac-KLK2 presented here further confirm the therapeutic potential of targeting KLK2 with a 225Ac-based radioconjugate for treating prostate cancer." (PMID 40627156, 2025). "By contrast, the data presented here show that KLK2 is expressed on the surface of prostate cancer cells and can be targeted via multiple therapeutic modalities." (PMID 40627156, 2025). "The KLK2 expression profile in different stages of prostate cancer and its cell surface expression were confirmed by IHC and multiplex immunofluorescent staining." (PMID 40627156, 2025). "To further characterize the expression profile of KLK2 in prostate cancer, we compared its expression patterns with those of PSMA in the same tumor samples." (PMID 40627156, 2025).
prostate carcinoma (continued). "KLK2 and HOXB13 have been reported to be strongly associated with the proliferation and metastasis of prostate cancer cells, and their expression levels were elevated in the invasive carcinoma regions." (PMID 40254832, 2025). "Taken together, our results show that KLK2 is a promising cell surface target for prostate cancer, addressable by a bispecific antibody (KLK2 × CD3), RLT (225Ac-KLK2), and KLK2-targeted CAR T cells." (PMID 40627156, 2025). "Robust expression of KLK2 was noted across the prostate cancer disease continuum, with homogeneous expression in LPC and mHSPC and increased heterogeneity in heavily pretreated mCRPC tissue samples." (PMID 40627156, 2025). "Targeting KLK2 with various MoAs represents novel therapeutic approaches for advanced prostate cancer." (PMID 40627156, 2025). "The introduction of KLK2 × CD3 increased interactions between prostate cancer target cells (VCaP) and T cells from healthy male donors 1.5× and 2× compared with a null × CD3 control construct or with coincubation with no bispecific antibody, respectively." (PMID 40627156, 2025). "The formation of an immune synapse via this bispecific antibody is intended to activate T cells by binding to CD3 and redirecting them to KLK2-positive prostate cancer cells, facilitating KLK2-specific T-cell activation and targeted tumor lysis." (PMID 40627156, 2025). "Human kallikrein 2 (KLK2) is a prostate-specific antigen expressed across the prostate cancer disease continuum." (PMID 40627156, 2025). "Taken together, these studies validate KLK2 as a surface target in prostate cancer and a KLK2 × CD3 T-cell engager as a potential therapeutic treatment." (PMID 40627156, 2025). "The main goal of this project was to identify transcriptomic, genomic, and immunologic cell correlates present in prostate cancer with a high expression of KLK2." (PMID 38396898, 2024). "In the present article, we evaluate the transcriptomic and immunologic profile of prostate cancer patients with a high expression of KLK2." (PMID 38396898, 2024). "T cell engagers based on KLK2, a kallikrein specifically expressed in prostate cancer (PRAD), are currently in early clinical development." (PMID 38396898, 2024). "Hu11B6 is a humanized IgG1 antibody that can get internalized to prostate cancer cells after binding to the catalytic cleft of human KLK2." (PMID 39272956, 2024). "For example, the eRNA KLK3e reportedly promotes chromatin interaction between its enhancer locus and KLK2 to activate KLK2 transcription in prostate cancer cells." (PMID 38177123, 2024). "According to the body of evidence from previous studies, human kallikrein‐related peptidase 2 (KLK2), a protease that is exclusively expressed in the prostate gland, can facilitate prostate cancer progression and act as a biomarker." (PMID 37232542, 2023). "Currently, a large number of studies have confirmed that KLK2 is closely related to prostate cancer, including diagnosis, pathological grade, stage and patient prognosis." (PMID 37593117, 2023). "Real-time PCR showed a significant induction of PSA, TMPRSS2, and KLK2 mRNA expression with the supplementation of 1 and 10 nM R1881 in LNCaP and VCaP prostate cancer cells." (PMID 37744273, 2023). "Quercetin exposure resulted in a dramatic decrease of KLK2 mRNA expression in both prostate cancer cell lines, endorsing the tumour‐inhibiting characteristics of this compound." (PMID 37232542, 2023). "The level of KLK2 in blood can be used as a biomarker for prostate cancer, and KLK2 is inactivated upon entering the bloodstream by binding to blood proteins." (PMID 33673582, 2021). "Deeper examination found the common thread linking down-regulated genes was involvement in proliferation, including several known to increase prostate cancer proliferation (KLK2, PCAT1 and VAV3)." (PMID 33596994, 2021).
prostate carcinoma (continued). "For example, among the top 10 up-regulated genes, KLK3 and KLK2, are highly enriched in prostate cancer, which are taken as effective biomarkers for diagnose and prognostic monitoring of prostate cancer." (PMID 33604283, 2020). "Studies give contradictory evidence towards KLK2’s use as a marker for detection of prostate cancer in combination with PSA." (PMID 32316460, 2020). "Similar to a previous study, in our study KLK2 was under-expressed in recurrent prostate cancer tissues compared with healthy tissues." (PMID 33150763, 2020). "The risk of prostate cancer has been reported associated with single-nucleotide polymorphisms (SNPs) located in the genes coding for PSA (KLK3) and hK2 (KLK2)." (PMID 31639059, 2019). "We recognized that the α-particle induced DNA damage and ensuing upregulation of AR and KLK2 would increase the prostate cancer targeting by [225Ac]hu11B6, creating an amplification loop for cell-specific therapy." (PMID 29691406, 2018). "We recognized that the alpha particle induced DNA damage and relied on ensuing upregulation of AR and KLK2 to addict the prostate cancer to the therapeutic [225Ac]hu11B6 agent." (PMID 29691406, 2018). "Data in this paper shows that decreasing LMTK2 expression in prostate cancer cells deprived of androgen results in significantly higher levels of FKBP51 protein as well as increased mRNA levels of AR-dependent genes (KLK2, S100P, TMPRS22 and PSA)." (PMID 26008968, 2015). "The biology of prostate cancer, particularly, the shared androgen dependence of PSA and hK2, taken together with our previous work adds to the mounting evidence that KLK2 is a prostate cancer susceptibility gene." (PMID 25279276, 2014). "Among the two KLK2 SNP variants, KL2 (rs198977) was positively associated prostate cancer at repeat biopsy (OR variant T allele = 1.81, 95% CI: 1.04-3.13, p = 0.049)." (PMID 25279276, 2014). "Due to its narrow tissue distribution, KLK2 has been regarded as a potential drug target in prostate cancer or as a prodrug activator in targeted chemotherapy." (PMID 25326387, 2014). "Of note, among the genes repressed by AMPK was KLK2, a prostate cancer marker and a well-established AR target gene that belongs to the same gene family (kallikrein-related peptidases) as prostate specific antigen (PSA / KLK3)." (PMID 25003216, 2014). "Folate hydrolase 1, also known as prostate-specific membrane antigen, and KLK2 have been studied as prostate cancer serum biomarkers." (PMID 22515324, 2012). "The authors mention that this result is notable considering KLK4 and KLK2 collaborate to stimulate cellular proliferation in prostate cancer." (PMID 22970239, 2012). "KLK2 is highly homologous to the PSA (KLK3) gene used in our mouse prostate cancer model for Cre expression." (PMID 19461893, 2009). "There is evidence indicating that KLK2 is more closely correlated to the total volume and higher grade prostate cancers than PSA." (PMID 19055846, 2008). "The list of 10 genes again included the well-established prostate cancer markers KLK2, KLK3 (PSA), FOLH1 (PSMA), PSGR (OR51E2), STEAP2, NKX3.1 and Prostein), and also included NCAM2, SPON2 and HOXB13." (PMID 15583692, 2005). "Our results showed that KLK2 expression is largely homogeneous across disease stages in prostate cancer, including advanced prostate cancer, and as such, KLK2 presents unique opportunities for the development of novel therapies in all stages of prostate cancer." (PMID 40627156, 2025). "KLK2 expression was more specific than that of other prostate cancer target antigens." (PMID 40627156, 2025).